SYP (synaptophysin)
Diseases named in the same sentence as SYP in open-access papers (continued):
Sharing a sentence is not in itself a finding about the gene and the disease.
brain injury (4 papers, 2011 to 2020). Acute and chronic (see also brain INJURIES, CHRONIC) injuries to the brain, including the cerebral hemispheres, CEREBELLUM, and brain STEM. "Traumatic and ischemic brain injury increases the level of Nogo-A, an axon growth inhibitor, and reduces synaptophysin, a synaptic protein, in adult rat brains, and exercise can counteract the effects of traumatic brain injury on Nogo-A and synaptophysin." (PMID 24260348, 2013). "Synaptic plasticity and neurotrophic factors (expression of synaptophysin, BDNF, TrkB) are involved in neurorepair activity, leading to functional recovery following acute brain injury." (PMID 21733162, 2011). "However, the finding that SYP+ presynaptic terminals are only partially protected and primarily in females, and spatial memory is only normalized in females suggests a crucial role for other, sex-dependent, and IFNAR1-dependent factors in HIV-induced brain injury that remain to be elucidated." (PMID 32727588, 2020).
glioneuronal tumor (4 papers, 2009 to 2025). "Tumors in this class included six GBM, one of which was a secondary GBM, one anaplastic astrocytoma, and one tumor with histopathologic features of GBM and synaptophysin positivity (“glioneuronal tumor”, GNT.15)." (PMID 19915670, 2009). "Looking in a supervised way at expression of particular differentiation markers commonly used for immunohistochemical analysis of glial/glioneuronal tumors, we found low GFAP expression, and modest levels of OLIG2, NeuN (RBFOX3), MAP2 and synaptophysin (SYP)." (PMID 34417833, 2021).
goblet cell carcinoid (4 papers, 2008 to 2024). "We observed a diffuse synaptophysin immune reaction in the endocrine cells of the goblet cell carcinoid." (PMID 18252007, 2008). "Based on our results we find out that apart from the described serotonin-, somatostatin- and chromogranin A-positive endocrine cells, the goblet cell carcinoid contains also synaptophysin-positive endocrine cells." (PMID 18252007, 2008). "In all cases of goblet cell carcinoid/MANEC, CgA and synaptophysin were present only in scattered neoplastic cells." (PMID 24695372, 2014). "Immunohistochemical testing was performed using synaptophysin, chromogranin A, neuronal specific enolase, CD56, CDX-2, CK20, CEA, MUC2 and Ki67, thus establishing the final diagnosis of high-grade extra-appendiceal goblet-cell adenocarcinoma of the cecum, G3." (PMID 40729214, 2024).
lung adenocarcinoma (4 papers, 2015 to 2025). A carcinoma that arises from the lung and is characterized by the presence of malignant glandular epithelial cells. "A biopsy from the lesion revealed an adenocarcinoma of the lung (TTF1-positive, negative for markers of neuroendocrine differentiation such as chromogranin A and synaptophysin 38)." (PMID 27776522, 2016).
lung carcinoids (4 papers, 2014 to 2024). "However, the detection of chromogranin, synaptophysin, and neuron specific enolase is necessary to confirm the diagnosis of lung carcinoid." (PMID 25705534, 2015). "To further ensure consistency of key expression patterns, we compare expression values of four markers of lung carcinoid tumors: NCAM1 (CD35), INSM1, SYP (synaptophysin), and OTP (orthopedia homeobox protein)." (PMID 38706317, 2024). "From an immunohistochemical viewpoint, lung carcinoids are positive for pan-cytokeratins and neuroendocrine markers of first- (CD56, chromogranin A, and synaptophysin) and second-generation lineages (INSM1)." (PMID 38001701, 2023).
pancreas tumors (4 papers, 2017 to 2022). "As a result, ductal (CA2, CK19, and SOX9)/pancreatic cancer (EpCAM and CD44) markers decreased and acinar markers (SYP and PTF1A) increased by inhibitor treatment in KiPCs." (PMID 33233448, 2020).
pilocytic astrocytoma (4 papers, 2012 to 2023). Pilocytic astrocytoma is a rare subtype of low-grade glioma of the central nervous system characterized by a well circumscribed, often cystic, brain tumor with a discrete mural nodule and long, hair-like projections that extend from the neoplastic astrocytes. "We also examined more tumor‐related markers in PDOs at day 28, such as YAP1 and p75 NGFR for SHH MB and synaptophysin for pilocytic astrocytoma (Fig EV3E–H)." (PMID 38037472, 2023). "Pathological study showed coexistence of areas of pilocytic astrocytoma with areas in which small rounded oligodendrocyte-like cells (OLC), with strong synaptophysin expression were identified." (PMID 22988535, 2012). "These tumors are considered to be more aggressive than pilocytic astrocytomas and immunohistochemically label strongly and diffusely for GFAP and vimentin but are negative for the neuronal markers synaptophysin, neurofilament, chromogranin and epithelial membrane antigen." (PMID 38983553, 2022).
small cell carcinoma of the bladder (4 papers, 2011 to 2023). "In this study, we compared the expression of cytokeratin, myogenin, synaptophysin and chromogranin in rhabdomyosarcomatous tumor and small cell carcinoma of the bladder." (PMID 21762516, 2011).
type 2 diabetes (4 papers, 2020 to 2025). "Consistent with the previous study, we observed the decreased expression of p-CREB, PKA-cα, synaptophysin, and PSD95 in type 2 diabetes mice." (PMID 32754028, 2020). "Long-term exercise training not only increases SYP and PSD-95 expression in the ischemic brain, promoting neural function recovery, but also enhances their expression in the hippocampus of rats with chronic stress and type 2 diabetes, thereby improving spatial learning and memory." (PMID 39984845, 2025).
adrenal pheochromocytoma (3 papers, 2016 to 2026). "Extra-adrenal pheochromocytoma shows NSE, chromogranin, and synaptophysin immunoreactivity." (PMID 27818820, 2016).
autism (3 papers, 2018 to 2022). Persistent deficits in social interaction and communication and interaction as well as a markedly restricted repertoire of activity and interest as well as repetitive patterns of behavior. "Finally, we evaluated the cellular and molecular autism-related phenotypes, including synaptophysin (SYP) expression and spine density." (PMID 35027651, 2022).
colorectal adenocarcinoma (3 papers, 2012 to 2026). The most common type of colorectal carcinoma. "In univariate analysis of the 1002 conventional colorectal adenocarcinomas, synaptophysin-expressing groups showed an association with DFS (p = 0.037), but not with OS or DSS." (PMID 34680258, 2021). "Our data suggest that synaptophysin expression in conventional colorectal adenocarcinomas is of minor prognostic relevance and that conventional adenocarcinomas with a diffuse synaptophysin expression should not be classified as MANECs." (PMID 34680258, 2021). "Usually, GCCs stain scattered positively for the neuroendocrine markers chromogranin A and synaptophysin but similar to the present case, they also produce mucin like colorectal adenocarcinomas." (PMID 23304574, 2012). "Our data thus suggest that synaptophysin expression in conventional colorectal adenocarcinomas without any component suggestive of a neuroendocrine differentiation in H&E-stained sections is of minor prognostic relevance, at best." (PMID 34680258, 2021). "We found no survival differences between synaptophysin expression groups within conventional colorectal adenocarcinomas." (PMID 34680258, 2021). "Furthermore, based on our data, we are not able to make further conclusions about the molecular underpinnings and possible differences in treatment response of synaptophysin-expressing conventional colorectal adenocarcinomas without a morphologically recognizable neuroendocrine component." (PMID 34680258, 2021).
COVID-19 (3 papers, 2022 to 2024). A disease caused by infection with severe acute respiratory syndrome coronavirus 2. "Recent studies reveal elevated levels of brain-reactive autoantibodies against MBP, MOG, tubulin, CP2, and synaptophysin in patients suffering from protracted COVID-19, suggesting a possible involvement of neuroautoimmune pathophysiology." (PMID 38560433, 2024). "Five hub genes, including GAD2, SST, TAGLN3, SYP, and KCNJ4, were further verified using the test_datasets of COVID-19, AD, and PD." (PMID 36902271, 2023).
cyst (3 papers, 2009 to 2020). A sac-like closed membranous structure that may be empty or contain fluid or amorphous material. "Additionally, the teratomatous cyst wall showed strong staining for smooth muscle actin, and weak staining for carbonic anhydrase IX, CD99, chromogranin and synaptophysin." (PMID 19523243, 2009). "Additionally, the teratomatous cyst wall was strongly and diffusely immunoreactive (3+, cytoplasmic staining) for smooth muscle actin (SMA); and weakly and focally immunoreactive (1+, cytoplasmic staining) for carbonic anhydrase IX (CA-IX), CD99, chromogranin and synaptophysin." (PMID 19523243, 2009).
embryonal tumors (3 papers, 2019 to 2024). "They comprise a well-defined methylation cluster separate from other embryonal tumors and should therefore be considered in young children with small round cell tumors that do not match any known tumor classes; most tumors are synaptophysin and OLIG2 positive." (PMID 38500181, 2024).
ganglioglioma (3 papers, 2018 to 2025). A well differentiated, slow growing neuroepithelial neoplasm composed of neoplastic, mature ganglion cells and neoplastic glial cells. "Ganglioglioma is characterized by the presence of true, well-formed ganglion cells with neuronal marker positivity (e.g., synaptophysin and MAP-2)." (PMID 41024929, 2025). "In Case 8 with a focal ganglioglioma component, stronger synaptophysin labelling of atypical ganglion cells was noted compared to the VC." (PMID 28833756, 2018).
ganglioneuroma (3 papers, 2011 to 2016). A benign neuroblastic tumor of the sympathetic nervous system that occurs in childhood. "Gastrointestinal stromal tumor, smooth muscle tumor, and adenocarcinoma can easily be excluded with immunohistochemical staining for S100 protein, synaptophysin, and/or chromogranin A. Ganglioneuroma lacks the epithelioid component, while GP usually shows a prominent epithelioid component." (PMID 28096810, 2016). "Differential markers for distinguishing ganglioneuromas from ganglioneuroblastomas at present are not available; immunohistochemical stains with antibodies such as neurofilament, synaptophysin, chromogranin, s-100 and LCA are generally positive in both ganglioneuromas and ganglioneuroblastomas." (PMID 21781292, 2011).
gastric adenocarcinoma (3 papers, 2020 to 2026). "However, the diagnosis can be challenging since primary gastric adenocarcinoma cells commonly exhibit partial synaptophysin immunoreactivity." (PMID 33214873, 2020). "Immunohistochemical analysis showed that these cells expressed cytokeratin 7 but not cytokeratin 20, CD117, CD34, chromogranin A, and synaptophysin, confirming the diagnosis of exophytic gastric adenocarcinoma with peritoneal dissemination." (PMID 42017098, 2026).
gastrointestinal stromal tumor (3 papers, 2016 to 2024). "Bcl-2 and vimentin are typically immunoreactive in SFTs in addition to CD34 and STAT6, but SMA and desmin (a marker for myocytes), S-100 and synaptophysin (a marker for perineural tissue), or c-kit (a marker for gastrointestinal stromal tumors) are generally negative." (PMID 39435031, 2024).
glaucoma (3 papers, 2016 to 2023). Increased pressure in the eyeball due to obstruction of the outflow of aqueous humor. "The decrease in synaptophysin expression in the retina may be due to the significant loss of RGCs in glaucoma; however, increased expression of PSD95 may suggest a compensatory mechanism to restore synaptic connections between RGCs and bipolar cells that were lost because of apoptosis." (PMID 36905120, 2023). "Synaptophysin was decreased in the retina under glaucoma conditions (p < 0.005), while its levels were rescued in the group treated with AAV-NS (p < 0.006)." (PMID 36905120, 2023). "In our previous study, synaptophysin expression gradually increased with glaucoma induction until 8 weeks after glaucoma induction." (PMID 31142572, 2019). "However, when exposed to experimental glaucoma, synaptophysin showed an increase (p < 0.02) in NS+/+ Tg mice, and PSD95 declined (p < 0.03), suggesting differential effects of NS expression change on pre- and post-synaptic biological processes." (PMID 36905120, 2023). "In PBS-treated glaucoma samples, where we did not see any signs of neurites outgrowth, also synaptophysin expression within GCL was absent." (PMID 27034151, 2016).
lymph node metastasis (3 papers, 2023 to 2025). "In this report, a lymph node metastasis with positive staining for chromogranin and synaptophysin was identified in the pathological analysis." (PMID 40242210, 2025).
malignant peripheral nerve sheath tumor (3 papers, 2012 to 2023). Malignant peripheral nerve sheath tumor (MPNST) is a rare and often aggressive soft tissue sarcoma occurring in a wide range of anatomical sites. "Malignant schwannomas show positive staining for vimentin and CD56 and negative staining for CK, LCA, CD34, SMA, desmin, chromogranin, and synaptophysin." (PMID 25276456, 2014).
Nephroblastoma (3 papers, 2017 to 2025). An embryonal neoplasm characterized by the presence of epithelial, mesenchymal, and blastema components. "Positive staining for neuroendocrine markers (NSE, synaptophysin, chromogranin A) and negative staining for lymphoid (CD3, Pax5) and nephroblastoma (WT1) markers were pivotal in confirming the tumor’s neuroendocrine origin." (PMID 40948633, 2025). "Immunohistochemistry in our case stained clearly positive for synaptophysin and vesicular monoamine transporter type 2 (VMAT2) whereas markers typically found in the majority of nephroblastomas were absent." (PMID 28818093, 2017).
neuroepithelial tumors (3 papers, 2013 to 2024). "The histopathological review demonstrated a morphologically heterogeneous group of high-grade neuroepithelial tumors with positive immunostaining for markers of glial differentiation in combination with weak and focal expression of synaptophysin, CD56 and CD99." (PMID 36964296, 2023).
prion disease (3 papers, 2008 to 2024). A transmissible disease that is caused by a protein that is able to induce abnormal folding of normal cellular proteins, leading to characteristic spongiform brain changes, which are associated with neuronal loss without an inflammatory response. "Synapse degeneration is also a feature of human and experimental prion diseases and the prion-derived peptide PrP82-146 triggered a reduction in synaptophysin in cortical neurons." (PMID 21138585, 2010). "Therefore, sequestration of cholesterol by PrPSc may affect synaptic transmission, a hypothesis supported by observations that ScGT1 cells contain altered amounts of synaptic proteins including synaptophysin and that synapse damage is seen during the early stages of experimental prion diseases." (PMID 18269734, 2008).
scrapie (3 papers, 2012 to 2021). A fatal disease of the nervous system in sheep and goats, characterized by pruritus, debility, and locomotor incoordination. "PIKfyve is highly expressed in neurons, yet the neuronal proteins NeuN and synaptophysin were unaffected, suggesting that its loss did not reflect the neuronal loss in scrapie‐sick mice." (PMID 34291577, 2021). "Using synaptophysin antibody which specifically labels membrane of synaptic vesicles both in the CNS and periphery, punctate granular labelling was observed surrounding cells of the medulla in both the scrapie infected and normal animals." (PMID 23469286, 2013). "This is consistent with published data where levels of synaptophysin have been found to decrease in brains of CJD patients and murine scrapie models." (PMID 22928663, 2012).
thymoma (3 papers, 2007 to 2017). A neoplasm arising from the epithelial cells of the thymus. "Only few studies have addressed the prevalence of neuroendocrine differentiation in human thymic neoplasms and demonstrated reactivity for synaptophysin, neuron-specific enolase, and/or chromogranin in 58% thymic carcinomas and atypical thymomas." (PMID 17498299, 2007). "But careful clinical and minimal immunohistochemical analysis might establish the right diagnosis, as thymomas do not express commonly used neuroendocrine (synaptophysin and chromogranin) markers." (PMID 28602157, 2017). "Even though both types of lesions share strong CAM 5.2 positivity, thymomas are negative for neuroendocrine markers (e.g. chromogranin A, synaptophysin, NCAM, and CD56) and may be useful for NECs." (PMID 21092193, 2010).
type 1 diabetes (3 papers, 2012 to 2024). "Western blot analysis showed a reduction of the immunoreactivity of synaptophysin (−23.3±4.9%, n = 6, P<0.05) and SNAP25 (−28.6±6.5%, n = 6, P<0.05) in hippocampal membranes, indicating the occurrence of synaptic degeneration, previously reported to occur in models of type 1 diabetes." (PMID 22514596, 2012).
acinar adenocarcinoma (2 papers, 2020 to 2022). "The majority of the tumor was acinar adenocarcinoma–positive for PSA; however, ∼10% of the tumor showed small-cell morphology, which stained positive for chromogranin A and synaptophysin." (PMID 35487690, 2022).
acute appendicitis (2 papers, 2021 to 2022). "Morphologically normal appendices removed owing to a clinical diagnosis of appendicitis were associated with increased expression of neuroimmune-endocrine mediators, with emphasis on synaptophysin, enolase, mast cell-related tryptase, and protein gene product 9.5 in the appendiceal wall." (PMID 33520210, 2021). "Similarly, there was a downregulation of the expression of neuroendocrine markers (chromogranin and synaptophysin) in acute appendicitis as compared to the other three groups." (PMID 35741196, 2022).
anemia (2 papers, 2019 to 2025). A reduction in the number of red blood cells, the amount of hemoglobin, and/or the volume of packed red blood cells. "In general, during anemia recovery, fermented goat milk diet consumption increased dopamine, oxytocin, serotonin, synaptophysin, and α-MSH, and decreased MAO-A and MAO-B, suggesting a potential neuroprotective effect in brain functions, which could enhance brain molecular functions." (PMID 31591353, 2019). "In addition, the results of the current study reveal that in general, during anemia recovery, a fermented goat milk-based diet, normal iron, or iron overload inhibits MAO activities, and increases serotonin, synaptophysin, and α-MSH levels." (PMID 31591353, 2019).
Astrocytoma (2 papers, 2016 to 2025). "Astrocytoma cells react strongly with GFAP and negatively with synaptophysin, neurofilament, desmin, cytokeratin, and epithelial membrane antibodies." (PMID 27568373, 2016).
brain tumors (2 papers, 2018 to 2025). "During routine diagnostics of brain tumours, we encountered an index case featuring “small blue round-cell” morphology, expression of TTF-1 and diffuse expression of synaptophysin." (PMID 39899075, 2025).
cerebral infarcts (2 papers, 2013 to 2022). "Modified neurological severity score (mNSS), cerebral infarction volume ratio, microglial activation, dendritic complexity, and expression of synaptophysin (Syn) and postsynaptic density protein 95 (PSD-95) were detected after 28 days of intervention." (PMID 35928570, 2022). "Distinctive alterations are seen with synaptophysin in cerebral infarcts, laminar necrosis of the cortex and other ischaemic lesions." (PMID 23883617, 2013).